MIR549A (microRNA 549a)
Synonyms: hsa-mir-549; MIR549; MIRN549; hsa-mir-549a; mir-549a
Gene: MicroRNA gene on chromosome 15 (80,841,978 to 80,842,073, reverse strand). Ensembl gene ENSG00000208003.
Gene Ontology:
Biological process: miRNA-mediated post-transcriptional gene silencing